RN7SL567P (RNA, 7SL, cytoplasmic 567, pseudogene)
Gene: Miscellaneous RNA gene on chromosome 3 (42,676,189 to 42,676,491, reverse strand). Ensembl gene ENSG00000240203.
Homologues: Orthologues: chimpanzee Metazoa_SRP (99% identical), macaque Metazoa_SRP (94% identical). Paralogues in human: RN7SL1 (82% identical), RN7SL2 (82% identical), RN7SL3 (81% identical), RN7SL296P (80% identical), RN7SL122P (79% identical), RN7SL481P (79% identical), RN7SL507P (79% identical), RN7SL493P (79% identical), RN7SL660P (79% identical), RN7SL18P (79% identical), RN7SL664P (79% identical), RN7SL126P (78% identical), and 700 more.